TNF (tumor necrosis factor)
Diseases named in the same sentence as TNF in open-access papers (continued):
Sharing a sentence is not in itself a finding about the gene and the disease.
psoriasis (continued). "Serum levels of TNF-α, IFN-γ, IL-2, IL-6, IL-8, IL-18, IL-22, chemerin, lipocalin-2, resistin, sE-selectin, fibrinogen, complement 3, and adiponectin correlate with psoriasis and can be used as potential biomarkers for psoriasis and response to the treatment." (PMID 29416693, 2018). "Although anti-tumor necrosis factor (TNF) agents are highly effective in the treatment of psoriasis, 2–5% of treated patients develop psoriasis-like skin lesions called paradoxical psoriasis." (PMID 29295985, 2018). "Tumor necrosis factor (TNF) is a proinflammatory cytokine that plays a significant role in a large array of inflammatory diseases such as arthritis and psoriasis." (PMID 29694513, 2018). "VALPHA is a fusion protein that targets both TNFα and VEGF-A and has shown to be effective in treating TPA induced psoriasis in mouse models." (PMID 29535706, 2018). "In classical psoriasis, the type I IFN response is rapidly replaced by increasing levels of TNF, which is critical for the maturation of cDCs that stimulate T cells." (PMID 29295985, 2018). "Cytokines have a very important role in the pathogenesis of psoriasis, especially those produced by Th1 cells (IFN-γ, IL-2, and TNF-α) and those produced by dendritic cells (IL-18, IL-20, TNF-α, and IL-23)." (PMID 29619128, 2018). "In resolved psoriasis lesions, the LC number is reduced after PUVA treatment and increased during anti-TNF treatment." (PMID 29520279, 2018). "The shift towards a Th1 dominated cytokine profile is supported by elevated TNF-α and IL-17A production from CD4+ T effector cells in psoriasis samples." (PMID 30054515, 2018). "The pooled serum levels of TNF-α, IFN-γ, IL-2, IL-6, IL-8, IL-18, IL-22, chemerin, lipocalin-2, resistin, sE-selectin, fibrinogen and C3 were higher in psoriasis patients compared with healthy controls (all P < 0.05)." (PMID 29416693, 2018). "For example, macrophages are the major source of TNF-α in psoriatic lesions and anti-TNF-α agents are approved for treatment of psoriasis." (PMID 30647534, 2018). "Recently, substantial studies have identified a central role of pro-inflammatory cytokines, including tumor necrosis factor α (TNF-α), interleukin (IL)-1β, IL-6, IL-23, and IL-17, in psoriasis pathogenesis." (PMID 29619028, 2018). "TNF downregulates the production of IFNs by the plasmacytoid DCs, thus TNF inhibition would enhance IFN production thereby favoring psoriasis development." (PMID 29751683, 2018). "In conclusion, this study identifies the relevance of the temporal equilibrium of TNF and type I IFN (TNF-IFN yin-yang) in the pathogenesis of paradoxical psoriasis." (PMID 29295985, 2018). "To validate the data obtained by microarray, we performed qRT-PCR and included AD like conditions (IL-4 and IL-13 treatment) as well as psoriasis like conditions (IL-22, OSM, IL-17, and TNFα treatment) in our experimental setup." (PMID 28928464, 2017). "The specific targets of biologics have out-pointed crucial cytokines, including tumor-necrosis-factor (TNF)-α, interleukin (IL)-23 and IL-17, for the development and maintenance of the skin changes in psoriasis." (PMID 29104241, 2017). "First, we only selected the serum level of IL-17, TNF-α, IL-6 to represent inflammatory cytokines to clear possible effects of MS on treatment of UVB in patients with psoriasis." (PMID 29390261, 2017). "We measured circulating TNF-α and IFN-γ in serum of patients with psoriasis against healthy controls." (PMID 29062018, 2017). "Strikingly, the common psoriasis/atherosclerosis gene set was disproportionately induced by IFN-γ (FDR = 1.47 × 10−11) and TNF-α (FDR < 0.01)." (PMID 29062018, 2017). "The 3D skin equivalents were incubated, up on day four for the following three days under AD like conditions (IL-4 and IL-13), psoriasis like conditions (IL-22, OSM, IL-17, and TNFα) or left untreated." (PMID 28928464, 2017).
psoriasis (continued). "Certolizumab Pegol, a PEGylated TNF-α inhibitor, has for several years been approved for PsA, and has now entered phase III trials for psoriasis." (PMID 29104241, 2017). "A. cinnamomea extract reduced psoriasis-like inflammation, infiltration of CD4+ T cells, CD8+ T cells, and neutrophils, and the expression of TNF-α, IL-17A, and IL-22 in imiquimod-induced psoriatic skin lesions." (PMID 28894754, 2017). "Among the diverse molecules related to this axis, tumor necrosis factor (TNF)-α, IL-23, IL-17 and IL-22 have been established as the key regulators of psoriasis based on the profound effects of biologics targeting these molecules." (PMID 29232931, 2017). "To date, five biologic agents targeting TNF-α have been approved for the treatment of rheumatoid arthritis, psoriatic arthritis, ankylosing spondylitis, juvenile idiopathic arthritis, IBD, psoriasis, and, most recently, hidradenitissuppurativa." (PMID 28420081, 2017). "Recent studies have also found interleukin 1β (IL-1β), tumor necrosis factor (TNF), vitamin D receptor (VDR), nitric oxide synthase 3 (NOS3), and other genes to be overexpressed in psoriasis patients (GOF)." (PMID 29292715, 2017). "Concomitant with elevated IFN-γ and TNF-α levels in blood of patients with psoriasis, TNFRI and TNFR-II were 1.2-fold and 21-fold higher in psoriasis compared to controls (p < 0.05 and p < 0.01)." (PMID 29062018, 2017). "TNF-α (pro-inflammatory) and IL10 (anti-inflammatory) are important cytokines in the pathogenesis of chronic inflammatory immune-mediated diseases such as psoriasis and IBD." (PMID 28486503, 2017). "Clinical studies have shown that neutralizing tumor necrosis factor-alpha (TNF-α), interleukin (IL)-12/23, or IL-17A is efficacious, demonstrating the central role of Th1/Th17 cells in psoriasis pathogenesis." (PMID 28865459, 2017). "Representatively, interleukin (IL)-17, IL-23, and tumor necrosis factor-α (TNF-α) initiate keratinocyte activation and hyper-proliferation, suggesting that these cytokines should commonly be considered markers of psoriasis." (PMID 26901187, 2016). "Studies on SpA and psoriasis patients report shifts in body mass, FM, and/or LBM after commencing anti-TNF medication." (PMID 27672678, 2016). "There is evidence for altered Wnt signaling in psoriatic skin, with higher Wnt5a expression in psoriatic plaques While anti-TNFα treatment decreases WNT5A gene expression to less than 75%, WNT5A remains part of the molecular profile of resolved psoriasis." (PMID 26849645, 2016). "TNF-α was inhibited by administration of adalimumab, a monoclonal antibody directed against TNF-α that has been licensed for use in psoriasis." (PMID 26943583, 2016). "These cells secrete a number of specific cytokines, including tumour necrosis factor (TNF)-α, interferon (IFN)-γ, interleukin (IL)-1, IL-6, IL-17A, IL-17F and IL-22, which play a role in the pathogenesis of psoriasis." (PMID 27936119, 2016). "Recently, there has been an increasing interest in the Th 17 cell pathway and related pro-inflammatory cytokines in psoriasis, including interleukin (IL)-17 and IL23, which induce the production of inflammatory mediators such as IL1, IL6, IL8, and TNF-α." (PMID 26910469, 2016). "Three TNF-α antagonists (adalimumab, etanercept and infliximab), and the IL12/23 monoclonal antibody (ustekinumab) are licensed for use in moderate and severe psoriasis." (PMID 27377373, 2016). "Biologics targeting tumor necrosis factor (TNF) or interleukins 12 and 23 (IL-12/23) are increasingly used to treat moderate-to-severe psoriasis." (PMID 26566272, 2015). "In psoriasis patients, TNF-α activates NF-κB, and TNF-α or TNF-α receptor inhibitors are very effective in suppressing inflammation." (PMID 25658361, 2015). "Therapies targeting TNF-α are now also recognized to be effective in multiple other chronic inflammatory diseases, including juvenile RA (JRA), Crohn’s disease, psoriasis, psoriatic arthritis, and ankylosing spondylitis." (PMID 26839814, 2015).
psoriasis (continued). "Tumor Necrosis Factor (TNF)-α and interferon (IFN)-γ have long been thought to play an essential role in psoriasis." (PMID 26691862, 2015). "CRP was reduced in patients from all three categories, TNF-α was reduced in patients with CFS and psoriasis, and IL-6 was reduced in those with UC and CFS all as compared to placebo." (PMID 27417751, 2015). "Unlike the other biological anti-psoriatic agents already brought to market, which all targeted TNFα, UST was the first-in-class anti-IL agent for psoriasis, representing an important milestone in rational drug design." (PMID 27747495, 2015). "Pro-angiogenic cytokines, especially tumor necrosis factor (TNF), are up-regulated in the psoriasis development." (PMID 25915746, 2015). "Many of the inflammatory analytes down-regulated during apremilast treatment in the current subset of PALACE 1 patients, including TNF-α, IL-8, IL-17, MIP-1β, and MCP-1, are over-expressed in patients with psoriasis and PsA." (PMID 25973439, 2015). "In addition, keratinocytes in psoriasis as well as synoviocytes in RA are capable of responding to direct IL-36 ligands stimulation with production of IL-6, IL-8, and antimicrobial peptides, which cooperate with IL-17A and TNF-alpha promoting neutrophil activation and migration." (PMID 25126586, 2014). "Inhibitors of TNF-α have been employed with increasing frequency for patients with a variety of inflammatory diseases, including RA, spondyloarthritis, IBD and psoriasis." (PMID 24968272, 2014). "In this mouse model, TNF-α, amphiregulin, HB-EGF and TGF-α were significantly up-regulated in the skin lesions, similar to human psoriasis." (PMID 25384035, 2014). "In summary, this study provides the proof of concept that sericin-based microspheres loaded with TNF-α-blockers could contribute to the down regulation of the cytokine and represents the starting point for the development of new topical formulations for the treatment of middle-stage psoriasis." (PMID 25101847, 2014). "Treatment of K5.Stat3C mice with TNF-α or EGFR inhibitors attenuated the skin lesions, suggesting the roles of TACE substrates in psoriasis." (PMID 25384035, 2014). "One of the proinflammatory cytokines, TNF-α, and growth factors of the EGFR ligand family represent essential mediators for the pathogenesis of psoriasis." (PMID 25384035, 2014). "TNF-α plays a crucial role in psoriasis; therefore, TNF inhibition has become a gold standard for the treatment of psoriasis." (PMID 25384035, 2014). "Enzyme immunoassay and immunohistochemistry analysis revealed that keratinocytes in psoriasis express and produce MMP-1 and MMP-19, which are decreased by anti-TNF-alpha." (PMID 24949467, 2014). "We found that certain markers that are overexpressed in women, such as C*07, TNF-308A and HLA-DR17 (DRB1*03), behave differently according to age at the onset of psoriasis." (PMID 23690822, 2013). "Since pituitary PRL secretion may be regulated by IFNγ and TNFα, albeit in rodent studies, and since these cytokines and PRL have been implicated in the pathogenesis of psoriasis, we also examined whether these prototypic pro-inflammatory cytokines influence PRL and PRLR expression in the HF." (PMID 23626671, 2013). "In psoriasis lesions, neutrophils accumulate and reinforce cytokine cascades by releasing IL-1α, IFN-α and TNF." (PMID 24260178, 2013). "A good example is the TNF-α molecule; the low estrogen concentrations typical of postmenopausal women have a stimulatory effect on the production of this cytokine, whereas high concentrations inhibit its synthesis, which could be crucial in the understanding of psoriasis in postmenopausal women." (PMID 24459670, 2013). "In psoriasis, IFN-gamma, the prototype Th-1 cytokine, interplays with IL-2, TNF-alpha, IL-17, and IL-22 to contribute to inflammation and altered differentiation." (PMID 23468834, 2013).
psoriasis (continued). "Psoriasis appears to be driven by a dysregulation of the innate immune system mediated by IFN-α, although several other inflammatory mediators, including TNF, are also involved." (PMID 23987103, 2013). "Stimulation with both TNF-α and IL-1β induced migration to CCL19 in both healthy individuals and patients with psoriasis (P < 0.05), with the effect being more pronounced in IL-1β-stimulated samples." (PMID 21933242, 2012). "Psoriasis is characterized by the upregulation of the cytokines IFN-α, IFN-γ, TNF-α, IL-17, IL-22, and IL-23, while TNF-α, IFN-γ, and Th17+ T cells have been shown to be important in HIV-1 controllers." (PMID 22577363, 2012). "The pro-inflammatory environment created by these anti-viral responses, resulting in the production of cytokines such as TNF-α and IFN-γ, would worsen the psoriasis." (PMID 22577363, 2012). "Another recent systematic review showed that there may be a small increased risk of overall infection with short-term use of TNF-α antagonists in psoriasis, whereas 97.6% were nonserious infections and the large majority of these were ones of the upper respiratory tract." (PMID 22645622, 2012). "The proportion of CD8+CCR4+ T cells is increased in the peripheral blood of patients with psoriasis and palmoplantar pustulosis, and CD8+CCR4+ T cells effectively produce IL-4, IFN-γ, IL-2, and TNF-α." (PMID 21483764, 2011). "In humans, iNOS and TNF positive CD11+ DCs are abundant in psoriatic skin lesions and are reduced following successful psoriasis treatment." (PMID 21295490, 2011). "CD11c also marks another subset of CD11c+/CD1c− DCs, which we havetermed “inflammatory dermal DCs”, or, in the case of psoriasis,“TIP-DCs” (TNF and iNOS-producing DCs)." (PMID 21541348, 2011). "We demonstrated that psoriasis-related transcripts, such as IFN-γ, TNF-α, IL-17A, CCL20, IL-23, IL-6, IL-1α and IL-22, were significantly enhanced in mouse ears treated with PL and rMCP-1 than those with 1×PBS control." (PMID 21311769, 2011). "Likewise, genes located farther from HLA-C at the centromeric end, including TNF-α (tumor necrosis factor-alpha), AGER (receptor of advanced glycosylation end product-specific receptor), HLA-DRB1, HLA-DQA1 and HLA-DQB1, have also been found to be associated with psoriasis." (PMID 19680446, 2009). "Psoriasis and SLE (or more frequently the appearance of ANA) have been described as an adverse effect of TNFα-blocker therapy." (PMID 19563672, 2009). "Bearing in mind that this interleukin actssynergistically with IL-1 and tumor necrosis factor alpha(TNF-α) further supports the hypothesis that IL-6 maycontribute via its receptor action to epidermal growth factor(EGF) function in modulating cell hyperproliferation in psoriasis." (PMID 16864908, 2006). "Moreover, the promising results obtained in both sarcoidosis and psoriasis patients after application of anti-TNF alpha agents (e.g. infliximab, adalimumab, etanercept) further support this hypothesis, since these therapeutic agents may alter pathogenic mechanisms common to both disorders." (PMID 17166281, 2006). "Serum tumor necrosis factor alpha (TNF-α), interleukin 1-beta (IL-1β), high-sensitivity C-reactive protein (Hs-CRP), sialic acid, and Sialic acid binding Ig-like Lectin-14 (Siglec-14) levels were investigated in controls and psoriasis patients." (PMID 41598424, 2026). "Additional relevant variables included age, IL-17, TNF, and IFN-γ, while others such as BMI, hs-CRP, TyG index, duration of psoriasis, duration of treatment, HbA1c, smoking, and IL-1β demonstrated negligible or negative importance, indicating limited contribution to model performance." (PMID 41601492, 2026). "Currently, biological agents, such as TNF-a inhibitors and antibodies against IL12/23 and IL17, are recommended as the first-line treatments for moderate-to-severe psoriasis, but some drawbacks including high cost, side effects, and drug resistance limit their applications." (PMID 40807399, 2025).
psoriasis (continued). "Psoriasis is characterized by the dermal and systemic secretion of certain pro-inflammatory cytokines of the Th1 and Th17 cytokine family, such as interferon-γ (IFN-γ), tumor necrosis factor (TNF), interleukin (IL)-6, IL-17, IL-22, and IL-23." (PMID 39775226, 2025). "Moreover, heat shock proteins (HSPs) such as HSP27, HSP60, HSP70, and HSP90 are overexpressed in psoriasis keratinocytes, acting as autoantigens that activate antigen-presenting cells via TLR4, promoting their maturation and the secretion of TNF-α and IL-12." (PMID 39859462, 2025). "Furthermore, co-culturing of psoriasis patient PBMCs with UC-MSCs significantly inhibited inflammatory cytokine production (IFN-γ, TNF, and IL - 17A) compared to controls, reinforcing the immunomodulatory properties of MSCs." (PMID 40969757, 2025). "Such reactions can include arthritis, psoriasis, and IBD, particularly with TNF inhibitors." (PMID 39807347, 2025). "Importantly, compared to free TFC, TFC-Exo exerted higher suppressive effects on the expression of TNF-α, IL-23, IL-6 and IL-15 and better therapeutic effects on IMQ-induced psoriasis in mice." (PMID 39861699, 2025). "Psoriasis and OSA also share common features such as the secretion of various mediators, including tumor necrosis factor (TNF)- α, intercellular adhesion molecule (ICAM)-1, E-selectin, and vascular endothelial growth factor (VEGF), which perpetuate inflammatory process." (PMID 40232659, 2025). "The pathogenic mechanisms about the Th17 axis have previously been reported together in psoriasis and systemic LE; here, apremilast blocks the production of INF-γ, IL-12, IL-23, and TNF-α, thus suppressing the Th1/Th17-mediated immune responses and exerting anti-inflammatory activity." (PMID 40918515, 2025). "Reports focused on paradoxical psoriasis following TNF‐alpha inhibitor use indicate that in patients who experienced paradoxical psoriasis with one TNF‐alpha inhibitor, switching to another anti‐TNF‐α agent led to a recurrence of lesions in about half of the cases." (PMID 39816706, 2025). "At the same time, M1 secretion of TNF-α and IL-18 and other pro-inflammatory factors promote Th1/Th17 cells to secrete IL-17A, IFN-γ and IL-21 and other inflammatory factors, which aggravates the inflammatory response of psoriasis." (PMID 40362523, 2025). "It is crucial to acknowledge that, despite the continuous development of various therapeutic agents for psoriasis, the overall non-response rate to TNF-α inhibitors remains significantly high, exceeding 30%." (PMID 40303401, 2025). "We demonstrated for the first time that the lack of mPGES-1 facilitates the expression of IL-17 A and TNFα in the skin in the mice with IMQ-induced psoriasis." (PMID 40481552, 2025). "IL-17 inhibitors have shown superiority in achieving skin outcomes in psoriatic arthritis compared with TNF inhibitors, and ASAS-EULAR recommends that IL-17 inhibitors may be preferred in patients with significant psoriasis." (PMID 40615873, 2025). "In addition, in the psoriasis group induced by IMQ, the levels of IL-1β, IL-6, TNF-α, and IL-17A were higher in the cko group than those in the wt group, especially IL-1β and IL-6 (p < 0.05)." (PMID 40430037, 2025). "KLRC1, KLRD1, PRF1, BIN2, and SLFN5 showed enrichment concentrated in immune-inflammatory modules—including IL-17 signaling, the TNF/NF-κB axis, and innate immune sensor pathways (NOD-, RIG-I-, and Toll-like receptors)—consistent with psoriasis-relevant Th17/innate activation." (PMID 41328434, 2025). "Thus, we aimed to analyze the mRNA expression of major cytokines, including IL-17 A, TNFα, and IFNγ in the skin of the IMQ-induced psoriasis pathological model." (PMID 40481552, 2025). "The TNF-α, MAPK, HIF-1α, and IL-17 signaling pathways were highly involved in the PPI network of 36 key targets of SHTLS, which are commonly recognized as major pathological features in the development of psoriasis." (PMID 40507893, 2025).